AP1M1 (adaptor related protein complex 1 subunit mu 1)
Description:
Subunit of clathrin-associated adaptor protein complex 1 that plays a role in protein sorting in the trans-Golgi network (TGN) and endosomes. The AP complexes mediate the recruitment of clathrin to membranes and the recognition of sorting signals within the cytosolic tails of transmembrane cargo molecules.
Synonyms: CLTNM; AP47; CLAPM2; mu1A; MU-1A
Tractability: Antibody: its Gene Ontology location is reachable by antibodies, with high confidence; UniProt places it where antibodies can reach, with medium confidence. PROTAC: ubiquitination databases record sites on it; its protein half-life has been measured.
Gene: Protein-coding gene on chromosome 19 (16,197,854 to 16,245,906, forward strand). Ensembl gene ENSG00000072958.
Subcellular location: Golgi apparatus; Cytoplasmic vesicle, clathrin- coated vesicle membrane
Subcellular location (Human Protein Atlas): Cytosol; Vesicles
Pathways (Reactome):
Immune System: MHC class II antigen presentation; Neutrophil degranulation
Vesicle-mediated transport: Golgi Associated Vesicle Biogenesis; Lysosome Vesicle Biogenesis
Disease: Nef mediated downregulation of MHC class I complex cell surface expression
Gene Ontology:
Molecular function: protein binding; clathrin adaptor activity
Biological process: endosome to melanosome transport; melanosome organization; Golgi to vacuole transport; melanosome assembly; platelet dense granule organization; vesicle-mediated transport; intracellular protein transport
Cellular component: extracellular exosome; membrane; AP-1 adaptor complex; cytoplasmic vesicle membrane; cytosol; early endosome; Golgi membrane; lysosomal membrane; plasma membrane; specific granule membrane; trans-Golgi network membrane; clathrin adaptor complex; clathrin-coated vesicle membrane; Golgi apparatus; synapse
Genetic constraint (gnomAD): Loss-of-function variants: 18 observed, 56.28 expected, observed/expected ratio (o/e) 0.32, 90% interval 0.22 to 0.47. The upper end of that interval is the gene's LOEUF score, 0.47, which puts it in group 2 of 6, group 1 being the genes least tolerant of losing a copy. Missense variants: 362 observed, 591.72 expected, observed/expected ratio (o/e) 0.61, 90% interval 0.56 to 0.67. Synonymous variants: 241 observed, 242.68 expected, observed/expected ratio (o/e) 0.99, 90% interval 0.89 to 1.11.
Homologues: Orthologues: chimpanzee AP1M1 (100% identical), dog AP1M1 (100% identical), pig AP1M1 (100% identical), mouse Ap1m1 (99% identical), guinea pig AP1M1 (99% identical), rat Ap1m1 (99% identical), zebrafish ap1m1 (98% identical), tropical clawed frog ap1m1 (96% identical), macaque AP1M1 (90% identical), Drosophila melanogaster AP-1mu (83% identical), Caenorhabditis elegans unc-101 (75% identical), rabbit AP1M1 (52% identical). Paralogues in human: AP1M2 (79% identical), AP2M1 (41% identical), AP3M1 (29% identical), AP4M1 (29% identical), AP3M2 (28% identical), STON2 (23% identical), STON1 (22% identical).
Diseases named in the same sentence as AP1M1 in open-access papers:
AP1M1 is named in the same sentence as 12 diseases in open-access papers, as found by Europe PMC text mining. Sharing a sentence is not in itself a finding about the gene and the disease. The quoted sentences say what the papers report.
breast tumors (1 paper, 2024). "This revealed that both EPI (e.g. LLGL2, CLDN4, KRT7, ST14) and MES (e.g. SNAI1, VIM, AP1M1) genes positively correlated with PIEZO1 expression across all quintiles, whilst markers of luminal breast tumors (ESR1, FOXA1, PGR) negatively correlated in all instances." (PMID 38632473, 2024).
colon cancer (1 paper, 2024). "In colon cancer, adaptor related protein complex 1 subunit mu 1 (AP1M1), subunit sigma 2 (AP1S2), and subunit sigma 3 (AP1S3) are common overregulated genes and might be related to the accumulation of IFITM3 protein on the cell surface." (PMID 39228892, 2024).
glaucoma (1 paper, 2016). Increased pressure in the eyeball due to obstruction of the outflow of aqueous humor. "Therefore we passed on the mentioned adjustments and consider the detected alterations in anti-AP1M1 ab and anti-SPSB3 ab over time in POAG + ODH as valuable hints to answer the question whether or not autoabs are relevant to glaucoma progression." (PMID 28030545, 2016).
liver cancer (1 paper, 2021). An epithelial or non-epithelial malignant neoplasm that arises from the liver. "However, upregulation of AP1M1 was reported to have pathological consequences; hepatitis B virus, the major cause of liver cancer, was found to cause upregulation of AP1M1 expression, which upregulated cancer cell proliferation." (PMID 34565296, 2021).
lung carcinoma (1 paper, 2026). "A systematic multi-omics analysis was conducted for the eight AP-1 adaptor complex genes (AP1AR, AP1B1, AP1G1, AP1G2, AP1M1, AP1M2, AP1S1, and AP1S3) to characterize their roles in lung cancer." (PMID 41438582, 2026).
schizophrenia (1 paper, 2025). A major psychotic disorder characterized by abnormalities in the perception or expression of reality. "Furthermore, we identified six genes—GRK2, KLF3, TAOK2, ARFGAP45, AP1M1, and GPAT2—that were shared across gene sets associated with both brain function and clinical symptoms, suggesting a common transcriptional basis for these features of schizophrenia." (PMID 41271614, 2025). "An intersection analysis revealed six genes-GRK2, KLF3, TAOK2, ARFGAP45, AP1M1, and GPAT2-common to both brain function and clinical symptomatology gene sets, highlighting a shared genetic etiology in schizophrenia’s neuroimaging and clinical manifestations." (PMID 41271614, 2025).
tumor (4 papers, 2016 to 2025). "The adaptor protein 1A complex (AP-1A), encoded by Ap1m1, is known to facilitate protein entry into vesicles, and blocking AP-1A led to the formation of immature secretory granules in AtT-20 corticotrope tumor cells." (PMID 27895892, 2016). "Three possible biomarkers associated with CNS metastases in TNBC tumours were identified: ISG15, THBS1 and AP1M1." (PMID 30792808, 2019). "In their study, samples from three groups (PA, residual PA, and CXPA) were analyzed to identify protein signatures and their results suggested that seven proteins (APOA1, AP1M1, SYCP1, DCD, HBB, HP, and SLC4A1) could be potential signatures for tumor progression or suppression." (PMID 39155517, 2025).
AP1M1 also shares sentences with these, for which no sentence is quoted: infection (2 papers); viral infection (2); cancer (1); fungal infection (1); thyroid cancer (1).